CD70 (CD70 molecule)
Diseases named in the same sentence as CD70 in open-access papers (continued):
Sharing a sentence is not in itself a finding about the gene and the disease.
lymphoma (continued). "Because lymphoma expressed a higher level of CD70 than lymphocytes, anti-CD70 antibodies might be a possible treatment for CD70 positive lymphomas." (PMID 31041299, 2019). "Furthermore, we also determined CD70 expression in 130 lymphoma samples and detected CD70 positive cells in all tested lymphoma subtypes, except for the NKTCL samples." (PMID 31652572, 2019). "Anti-CD70 immunostaining on positive RCC sections was much stronger than that of the lymphomas in our study, and quantitative RT–PCR results also showed an overall higher level of CD70 gene transcription in RCC, indicating that the protein is highly over-expressed." (PMID 16892042, 2006). "We explored the therapeutic potential of CD70 as target for CAR natural killer (NK) cell therapy in CRC, PDAC, focusing on tumor cells and CAFs, and lymphoma." (PMID 38331849, 2024). "CD70 promoted ox-LDL efflux in MØ while engineered anti-CD70 increased MØ phagocytosis and prolonged the survival in lymphoma mice." (PMID 28738836, 2017). "Our study also identified CD70 expression on B-cell malignancy-derived cell lines using FACS analysis, and on six out of twenty clinical lymphoma specimens by immunostaining." (PMID 16892042, 2006). "Single-cell transcriptomics confirms this approach prevents exhaustion and restores antitumor efficacy in lymphoma PDX models, while simultaneously reducing renal toxicity by eliminating CD70 from T cells that could exacerbate off-target damage." (PMID 40896423, 2025). "Notably, CD70-specific CAR-NK cells engineered to express IL-15 showed enhanced proliferation, persistence, and cytotoxicity against lymphoma cells in vitro and in vivo models." (PMID 40806636, 2025). "In 2022, CRISPR Therapeutics incorporation published the results of their Phase I clinical trial in the United States of two allogeneic CAR-T therapies targeting CD70 for the treatment of certain lymphomas and certain solid tumours, as well as CD19 for the treatment of leukaemia and lymphoma." (PMID 39427211, 2024). "Although some studies have previously evaluated the CD70 expression in solid tumors and in lymphomas, the evaluation of CD70 expression in AML patients in a clinical setting has not been explored." (PMID 38388965, 2024). "Interestingly, in some tumors, such as lymphoma, expression of CD70 on tumor cells and APCs improved anti-tumor immunity, whereas, in others, this CD27/CD70 signaling led to decreased anti-tumor immunity and increased Treg populations." (PMID 37174089, 2023). "Our results thus suggested that dual blockade of the CD70/CD27 and PD‐1/PD‐L1 pathways could hamper lymphoma growth in vivo, at least partially through rescue of T‐cell exhaustion." (PMID 36471481, 2022). "Vorsetuzumab mafodotin was evaluated in a phase I dose-escalation study in patients with R/R CD70-positive lymphomas or metastatic renal cell carcinoma (RCC) without sufficient activity to support further clinical development (NCT01015911)." (PMID 36654819, 2022). "Additionally, CD70+ lymphoma B cells also exert remarkable roles in inducing the transcription of Foxp3 in intertumoral CD4+ T cells and the interaction of CD27/CD70 is involved in this process." (PMID 36211467, 2022). "Although the role of CD70 has increasingly been investigated in the context of interplays across various immune cells and cancer cells, lymphoma SCs have not been explored as a source of CD70." (PMID 35332263, 2022). "CD70, a ligand of CD27, is expressed on activated T-cells, B-cells, and lymphoma." (PMID 31041299, 2019).
lymphoma (continued). "Finally, in a murine lymphoma model, we demonstrated that blocking the CD70/CD27 and/or PD1/PD‐L1 interactions could reduce CD70+ lymphoma growth in vivo, by directly impairing the tumour cell proliferation and rescuing the exhausted T cells." (PMID 36471481, 2022). "Moreover, the co-expression of CD70 and CD27 was observed in 39% of lymphoma samples." (PMID 31652572, 2019). "Our patient lacked CD70 expression, had an EBV+ lymphoma, and showed impaired CD8+ T-cell memory and effector functions." (PMID 33996677, 2021).
acute myeloid leukemia (24 papers, 2019 to 2026). Acute myeloid leukemia (AML) is a group of neoplasms arising from precursor cells committed to the myeloid cell-line differentiation. "Moreover, blockade of the CD70/CD27 interaction has been associated with the downregulation of stemness-associated genes in acute myeloid leukemia blasts, suggesting that CD70/CD27 signaling contributes to a more undifferentiated and malignant state." (PMID 40876452, 2025). "The up-regulation effect was also identified in the Molm13 cell lines (acute myeloid leukemia cell, moderate-high CD70 expression)." (PMID 36932256, 2023). "Immunotherapy strategies aiming to eradicate tumors by targeting the CD70-CD27 axis, mostly targeting CD70, have been explored principally in the context of acute myeloid leukemia." (PMID 36969173, 2023). "In this regard, a breakthrough was recently achieved for cusatuzumab (ARGX-110), an anti-CD70 targeting antibody, in combination with Azacitidine in a Phase 1/2 trial in acute myeloid leukaemia (AML)." (PMID 31652572, 2019). "Finally, the improved antigen sensitivity of CD70 specific CAR T cells eventuated in an enhanced therapeutic efficacy in a stress model of acute myeloid leukemia." (PMID 38090558, 2023). "Moreover, CD70/CD27 coexpression has been detected in acute myeloid leukaemia (AML) blasts and stem/progenitor cells, and its expression activates the stem cell gene expression program." (PMID 36471481, 2022). "Thereof, 92% response rates could be seen in acute myeloid leukaemia patients while using CD70-targeting antibodies in a Phase 1 trial." (PMID 31652572, 2019). "In a phase I clinical trial, targeting CD70 with cusatuzumab resulted in the elimination of LSC in patients with acute myeloid leukemia (AML)." (PMID 38561775, 2024). "Phase 1 and 2 trials are ongoing with cusatuzumab, a first-in-class anti-CD70 monoclonal antibody, in acute myeloid leukemia (AML) in combination with azacitidine and/or venetoclax (NCT04150887)." (PMID 37093350, 2023). "Therapeutically, CD70-targeted immunotherapy has been primarily evaluated in patients with hematologic malignancies, such as acute myeloid leukemia (AML) and B cell lymphoma." (PMID 37024479, 2023). "In addition, more CAR-T therapies targeting other cancers are under preclinical and clinical studies, such as mesothelin-targeting CAR-T cells to treat ovarian cancer, and CD70-targeting CAR-T cells to treat acute myeloid leukemia (AML)." (PMID 39851334, 2025). "In acute myeloid leukemia (AML), blocking the interaction between CD70/CD27 may promote the asymmetric differentiation and division of AML cells, further inhibiting tumor proliferation." (PMID 36358792, 2022). "Acute myeloid leukemia (AML) remains a therapeutic challenge, but CD70’s expression on leukemic blasts, not hematopoietic stem cells, positions it as a viable CAR-T target." (PMID 40896423, 2025).
B-cell lymphomas (22 papers, 2015 to 2025). "Therefore, this study aimed to investigate stimulated antibody production, polyclonal vs. virus-specific T-cell response, and cytokine production of a CD70-deficient patient reported previously with early-onset antibody deficiency suffering from chronic viral infections and B-cell lymphoma." (PMID 33996677, 2021). "To verify our measuring system, we detected the expression level of CD70 on primary non-Hodgkin B-cell lymphoma (B-NHL) cells (generally acknowledged to have a high CD70 expression) under the same condition." (PMID 36932256, 2023). "Apart from CD27 signaling, CD70 reverse signaling was also reported to increase proliferation in a low-grade B cell lymphoma." (PMID 34991665, 2022). "CD70-targeting CAR-T therapy is effective against CD19-negative B-cell lymphoma and gives rise to an alternative treatment for CD19-negative cancers." (PMID 36239354, 2022). "Three anti-CD70 ADCs have been investigated in phase I trials in patients with CD70-positive R/R B-cell NHL and metastatic RCC." (PMID 31500657, 2019). "Like CD27‐, CD70‐deficient patients, RASGRP1‐deficient patients appear to be particularly prone to develop EBV‐driven B‐cell lymphoma as the four patients described today had Hodgkin lymphoma." (PMID 29282224, 2018). "CD70 is overexpressed on both T and B-cell lymphomas with the highest incidence in diffuse large B-cell lymphoma (DLBCL)." (PMID 28915592, 2017). "Previous studies have demonstrated that HBV infection of B cell lymphomas can alter B-cell-specific signaling pathways by enhancing overall gene mutations, including CD70, or by increasing non-silent mutations or gene translocations, such as BCL6." (PMID 39532842, 2024). "In addition, CAR-T immunotherapy targeting CD70 also has potential therapeutic effects on leukemia and B-cell lymphomas." (PMID 36239354, 2022). "There are a number of ongoing clinical trials of CAR-T cell therapy targeting BAFFR receptors in patients with r/r B-cell NHL (NCT05370430) and CD70 in patients with CD70-positive malignant hematological diseases, including patients with NHL (NCT04662294)." (PMID 40726984, 2025). "We demonstrated that scFv-based anti-CD70-CAR-T cells efficiently killed both CD19+ and CD19- B-cell lymphoma cells." (PMID 36845088, 2023). "Furthermore, TGF-β induced upregulation of CD70 expression via Smad3 and IL-2/STAT5 signaling, resulting in exhaustion of effector memory T cells in B cell NHL." (PMID 34991665, 2022). "LOAd703 could infect and replicate in B-cell lymphoma cell lines (BC-3, Karpas422, Daudi, DG-75, U-698) and induced an overall enhanced immunogenic profile with upregulation of co-stimulatory molecules CD80, CD86, CD70, MHC molecules, death receptor Fas and adhesion molecule ICAM-1." (PMID 33666760, 2021).
breast carcinoma (22 papers, 2016 to 2025). "Several expression models based on CD70 in breast cancer are used as biomarkers of lung-specific metastasis." (PMID 36308553, 2023). "The modified CAR-T cells can specifically bind to CD70 and have a higher persistence and antitumor capacity on CD70-positive breast cancer cells." (PMID 35935930, 2022). "In breast cancer, these CD70 expressing CSCs displayed a mesenchymal phenotype, self-renewal potential and enhanced metastasis to the lung compared to the CD70− CSCs population that exhibited an epithelial phenotype." (PMID 34991665, 2022). "CD70+ population is useful in isolating CSCs from breast cancer cell lines, and CD70+ CSCs had significant self-renewal capacity and promoted lung-metastasis." (PMID 33964962, 2021). "TanCAR-T cells targeting CD70 and B7-H3 exhibit enhanced antitumor functionality in breast cancer." (PMID 35935930, 2022). "have reported that CD70+ breast cancer stem cells preferentially metastasize to the lungs." (PMID 34367975, 2021). "As the inhibitors of PD-L1, which is encoded by the CD274 gene, are already in clinical use and the gene product of CD70 is another potentially interesting immunotherapy target, we focused on the CD274:CD70 interaction in the context of IFNγ expression in breast cancer." (PMID 37106127, 2023). "Apart from that, there was a phase I/II clinical trial of CD70-CAR-T cell therapy for breast cancer patients suspended without reason reported (NCT02830724)." (PMID 35414783, 2022). "Likewise, epigenetic silencing of CD70, a CD80 related co-stimulatory molecule, by DNA methylation was noted during breast cancer progression in an in vitro model." (PMID 27377375, 2016).
ovarian carcinoma (19 papers, 2010 to 2025). A malignant neoplasm originating from the surface ovarian epithelium. "As studies show, elevated expression of CD70 is associated with drug resistance and poor prognosis, but in this case, the expression was studied in advanced ovarian cancer specimens." (PMID 35204342, 2022). "In ovarian carcinoma, CD70 expression on tumor cells was associated with clinical resistance to cisplatin." (PMID 34991665, 2022). "Also, the association between CD70 and clinical cisplatin resistance and poor prognosis of advanced ovarian cancer has been recorded, yet the precise mechanism remains to be elucidated." (PMID 35155224, 2022). "Although the mechanism through which chemotherapy induces CD70 expression is still largely unknown, our findings are similar to recent studies in ovarian cancer, where increased CD70 expression has been shown to associate with clinical resistance to cisplatin-based chemotherapy." (PMID 25951351, 2015). "conjugated vorsetuzumab with MMAF to form a CD70‐ADC for the treatment of platinum‐resistant ovarian cancer." (PMID 40629902, 2025). "CD70 is a transmembrane ligand overexpressed in several solid tumors (including ovarian cancer), with minimal presence on normal tissues." (PMID 40940995, 2025). "CD40 and CD70 are detected on a wide range of cancer cells (including ovarian cancer cells) and cells from their microenvironment." (PMID 33287223, 2020). "The results of this study support extending the clinical study of SGN-75 to pancreatic and ovarian cancer patients with tumours that express CD70." (PMID 20664585, 2010). "In agreement with our ovarian carcinoma data, CD70 has recently been reported as a potential cisplatin resistance marker in ovarian cancer using proteomic methods." (PMID 20664585, 2010). "In vitro, the ovarian cancer cell line SK-OV-3 had the highest level of CD70 detected by qFACS (2.2 × 105 antigens per cell), whereas the Panc-1 cell line had 1 × 104 antigens per cell." (PMID 20664585, 2010). "To confirm the IHC data, we performed quantitative fluorescence activated cell sorting (qFACS) on various pancreatic and ovarian cancer cell lines using an anti-CD70 mAb that is different from 1C1 and 5D12." (PMID 20664585, 2010). "Exploiting CD70’s tumor-specific expression and immunosuppressive role, early studies have evaluated CD70-targeted CAR T-therapies in gynecologic cancers including ovarian cancer." (PMID 40940995, 2025). "For example, CXCR2-modified GPC3-CART had improved trafficking in a hepatocellular carcinoma model, while a CXCR1/2-modified CD70-CART enhanced CART trafficking and efficacy in murine GBM, ovarian cancer and pancreatic cancer models." (PMID 35273619, 2022). "For CD70, which forms a molecular pathway with CD27, we demonstrated this increased concentration in the peritoneal fluid of ovarian cancer patients." (PMID 35204342, 2022). "The cutoff values for BTLA, CD27, CD70, CD28 and CD80 that were elevated in the serum of patients with ovarian cancer were calculated using ROC curve analysis." (PMID 35204342, 2022). "Notably, a few Phase I trials (e.g., NCT05518253, NCT06215950, NCT05420545, NCT05468190) are investigating the safety and efficacy of CD70 CAR T-cells in advanced/metastatic solid tumors, including epithelial ovarian cancer." (PMID 40940995, 2025). "Although SGN‐75 showed significant antitumour activity in pancreatic and ovarian cancer models, the first‐in‐human NCT01015911 study recruiting CD70‐positive metastatic RCC and non‐Hodgkin lymphoma (NHL) sufferers revealed that its clinical efficacy did not meet expectations." (PMID 40629902, 2025). "We further detected same pattern of c-IAP1, c-IAP2 and survivin in protein levels, suggesting 3PO could sensitize ovarian cancer cells via altering expression of c-IAP1, c-IAP2, survivin and CD70." (PMID 35155224, 2022).
ovarian carcinoma (continued). "In addition, our expanded IHC analysis of CD70 identified other indications, in which an anti-CD70 ADC could potentially be tested, most notably a significant fraction of pancreatic and ovarian carcinoma cases." (PMID 20664585, 2010). "Hence, to control for this variation, we sorted CD70+ and CD70– cells from the ovarian cancer cell lines PEO1, CaOV-2 and lung H1299 and compared their growth properties in soft agar to determine the effects of presence or absence of CD70." (PMID 29721188, 2018).
renal carcinoma (15 papers, 2006 to 2024). A carcinoma arising from the epithelium of the renal parenchyma or the renal pelvis. "By the pathology atlas of survival analysis, CD70 is a prognostic marker and high expression is unfavorable in renal cancer." (PMID 38637886, 2024). "A CD70-TTC has been shown to reduce cell viability in renal cancer cell lines and significantly inhibit tumor growth in a renal cancer xenograft model." (PMID 36726355, 2022). "For example, the Cluster of Differentiation 70 (CD70) gene is flagged by THPA and high CD70 expression is prognostic unfavorable for renal cancer." (PMID 31956905, 2020). "In agreement with this, our data showed that CD70 is expressed in many ovarian, lung, brain and kidney carcinoma cells and CD70+ cells also have increased colony forming activity in soft agar compared to CD70– cells (Table." (PMID 29721188, 2018). "CD70 is an ideal target for antibody-based therapies because of its aberrant high expression in renal carcinomas and non-Hodgkin lymphomas and its highly restricted expression in normal tissues." (PMID 20664585, 2010). "CD70 is an antigen that fulfils all of these criteria, in that it is highly overexpressed in a large proportion of renal carcinomas, whereas normal tissue expression is low and restricted to a subset of peripheral blood lymphocytes, and internalises in response to specific antibody binding." (PMID 16892042, 2006). "Moreover, the expression of CD70 in renal carcinoma cell lines induces apoptosis of lymphocytes." (PMID 35145909, 2021). "In this study, we screened a novel anti-CD70 scFv and generated CD70 CAR-T cells that showed effective antitumor functions against CD70+ renal carcinoma cells (RCCs) both in vitro and in vivo." (PMID 34556152, 2021).